GCNT3 (glucosaminyl (N-acetyl) transferase 3, mucin type)
Diseases named in the same sentence as GCNT3 in open-access papers (continued):
Sharing a sentence is not in itself a finding about the gene and the disease.
tumor (continued). "Next, we analyzed whether the partial changes in sLeA/X expression and static E-selectin binding upon GCNT3 kd also lead to notable alterations in the tumor cells’ capability to dynamically bind to E-selectin and to adhere on cytokine-stimulated HUVECs under laminar flow conditions." (PMID 39547084, 2025). "Furthermore, we analyzed the effects of GCNT3 depletion on the tumor cell glycome." (PMID 39547084, 2025). "Therefore, we hypothesized that this result may underestimate the actual efficacy of GCNT3 tumor inhibition." (PMID 37996891, 2023). "Future in vitro studies on GCNT3 should consider our observation that tumor cells might increase GCNT3 levels across the first passages after revitalisation, suggesting that the glycosylation machinery of tumor cells needs some time to adapt to culture conditions after thawing." (PMID 39547084, 2025). "The interaction between GCNT3 and ST3GAL1 further reveals the complex regulatory mechanisms of O-glycosylation and sialylation in tumor progression." (PMID 40352586, 2025). "Some of the glycoTs genes such as GCNT3, GALNT5, FUT3, B3GNT6 and B3GNT3 were more than 19-fold overexpressed in tumour samples." (PMID 32203219, 2020). "Four genes, G6PD, APLP1, GCNT3, and PLPP2, were also over-expressed in advanced stage (III and IV) and high grade (3 and 4) ccRCC and tumor with necrosis (PADJ<0.05)." (PMID 30603059, 2018). "Moreover, relatively high level of GCNT3 and GALNT5 was observed in tumor tissues and predicted worse prognosis in patients from GEO database." (PMID 35970845, 2022). "SPP1 and GCNT3 were differentially expressed between LUAD or LUSC and non-tumor controls." (PMID 35399076, 2022). "Previous studies of our group suggested that GCNT3 could be a potential marker for good prognosis in CRC and it might also be a biomarker to monitor tumor response to chemotherapy in these patients." (PMID 29855486, 2018). "In addition, we analyzed the gene expression profile of GSE85841 that included eight LUAD samples and adjacent non-tumor samples with adjusted P < 0.05 and logFC≥1.5, and researched the top five most significantly upregulated genes: SFRP5, CST2, SPP1, GCNT3, and NHLRC1." (PMID 35399076, 2022).
cancer (13 papers, 2013 to 2025). A tumor composed of atypical neoplastic, often pleomorphic cells that invade other tissues. "Together, these results expand upon the classical GCNT3-associated functions and provide us new insights about GCNT3 transcriptional networks in cancer cells." (PMID 29855486, 2018). "Our study points out VEGFA as an important player in GCNT3-associated functions in cancer and drug resistance." (PMID 29855486, 2018). "Moreover, our data suggest that different metabolic performances are associated with a GCNT3 increase in cancer cells." (PMID 29855486, 2018). "As for elongation, B3GNT3, B3GNT4, and GCNT3 were highly expressed in both cancer types (LUAD and LUSC)." (PMID 40718829, 2025). "To test the immune suppressive role of mucin barrier in a realistic model and to address the role of GCNT3 and mucins in immune escape, we established an in vitro recognition platform to track the cellular interactions between cancer and T cells." (PMID 37996891, 2023). "qRT-PCR showed that GCNT3 levels were nearly 3 times higher in cancer tissues than in normal tissues." (PMID 35399076, 2022). "We aim to explore the potential utility of GCNT3 as marker of prognosis and response to treatment in other types of cancer that were frequently diagnosed at advanced stages." (PMID 29855486, 2018). "Our results demonstrate a cancer suppressive activity of GCNT3, as its re-expression is accompanied by diminished protumoral characteristics such as growth, invasion and OCR." (PMID 29855486, 2018). "To elucidate how cancer cells modify their carcinogenic properties upon GCNT3 modulation, we performed cell growth and invasion experiments in our GCNT3 cellular models." (PMID 29855486, 2018). "In order to investigate the role of GCNT3 as cancer prognostic factor as well as its relationship with drug resistant, we analyzed mRNA and protein expression levels of GCNT3 in a panel of several CRC cell lines." (PMID 29855486, 2018). "In order to further investigate the role of GCNT3 as a biomarker for cancer patients, here, we took an integrated analysis of GCNT3 landscape of interactors and regulators." (PMID 29855486, 2018). "We moved the GCNT3 expression analysis to EOC where, clinically, better or alternative methods to identify cancer risk groups are also needed." (PMID 29855486, 2018). "The results obtained in this study provide us new insights into GCNT3 transcriptional and proteomic networks, and confirm the involvement of GCNT3 in relevant biological processes and pathways related to cancer and drug resistance." (PMID 29855486, 2018). "The mucin-type core 2 1,6-N-acetylglucosaminyltransferase enzyme (C2GnT-M), encoded by the GCNT3 gene, is a glycosyltransferase enzyme whose expression is altered in cancer processes." (PMID 29855486, 2018). "The non-secreted IHC biomarkers can be used for annotation of small biopsies in order to identify the cancer and, except for GCNT3, they are informative for distinguishing AC from SCC." (PMID 24299561, 2013). "Little is known about the functional role of GCNT3 in cancer metastasis." (PMID 39547084, 2025). "We showed that GCNT3 inhibition by talniflumate disrupts the expression of both membrane and secreted mucins impairing the formation of an immune suppressive barrier that protects cancer cells from T cells." (PMID 37996891, 2023). "To further investigate GCNT3 effect on reducing the malignant behavior, we checked the glycolytic potential, as the aerobic glycolysis is one of the most remarkable features of proliferative cancer cells." (PMID 29855486, 2018). "Additionally, there was an inverse correlation between GCNT3 and miR-195-5p in cancer." (PMID 35399076, 2022). "Glucosaminyl (N-acetyl) transferase 3, mucin type (GCNT3), is a novel core mucin synthase that plays a role as a cancer-promoting factor in gastric, colon, ovarian, and lung cancers." (PMID 35399076, 2022).
cancer (continued). "GCNT3 is not expressed in normal or cancer-derived prostate cells, but is variably expressed in other cancer types." (PMID 41011627, 2025). "In many cancer cells, both core 3 and 4 synthesis by B3GNT6 and GCNT3 showed altered activity." (PMID 41011627, 2025). "In hepatocellular carcinoma, GCNT3 is also downregulated in metastatic compared to non-metastatic clinical cancer specimens." (PMID 39547084, 2025). "Thus, GCNT3 role in cell invasion and drug resistance could be mediated through VEGFA in these two different cancer models, CRC and EOC, with relevant clinical implications." (PMID 29855486, 2018). "Additionally, CTRP (Cancer Therapeutics Response Portal) database was applied to detect the drug sensitivity of MUC1 and related glycosyltransferases to numerous clinical chemotherapeutics and found most of them were positively corelated with drug resistance, especially MUC1, GCNT3, and GALNT5." (PMID 35970845, 2022).
infection (6 papers, 2011 to 2023). The state of being infected such as from the introduction of a foreign agent such as serum, vaccine, antigenic substance or organism. "The most prominent modulation of expression of glycosyltransferase-encoding genes associated with glycan-core formation was observed for GCNT3 (plays a key role in both glycan core 2 and 4 biosynthesis) in association with RVC and G9P infection." (PMID 37848925, 2023). "GCNT3 protein expression was elevated 3.5 fold during primary infection; and its elevated expression was maintained during reinfection but to a lesser extent (2.4 fold) compared to drug-treated controls." (PMID 21414188, 2011). "Soon after infection of the bovine GI tract, both C. oncophora and O. ostertagi induced expression of the mucin glycan biosynthesis enzyme gene Gcnt3, in addition to Gcnt4 and A4gnt induced by O. ostertagi, further supporting that changes in the mucus niche occur during infection." (PMID 29912166, 2018). "Interestingly, in a previous study on cattle infected with C. oncophora, strong upregulation of GCNT3 in intestinal goblet cells and in columnar epithelial cell was noticed throughout the infection." (PMID 21569362, 2011). "Interestingly, GCNT3 mRNA followed the same pattern as MUC2, which were strongly up-regulated only during primary infection, compared to naïve controls." (PMID 21414188, 2011). "To test the hypothesis of a Gcnt3 compensatory activity in Gcnt1 null mice, we evaluated the transcription levels of Gcnt3, upon infection but no significant changes were found when comparing WT and Gcnt1-/- mice (data not shown)." (PMID 33406734, 2021). "For the glycosyltransferases involved in mucin biosynthesis, GCNT3 and GCNT4, both involved in the synthesis of core structures, were found to be up-regulated during infection, while C1GALT1 a key enzyme for the core 1 formation was not affected by the infection." (PMID 21569362, 2011).
adenocarcinoma (2 papers, 2015 to 2023). A common cancer characterized by the presence of malignant glandular cells. "In particular, expression of the GlcNAc transferases GcNT3 (one of the GlcNAcTs responsible for the synthesis of the core 2 O-glycan structures) and B3GNT3 (responsible for the synthesis of the extended core 1 O-glycan structure) were found to be markedly increased in the adenocarcinoma tissues." (PMID 26042789, 2015).
GCNT3 also shares sentences with these, for which no sentence is quoted: colitis (2 papers); allergic rhinitis (1); Alzheimer disease (1); benign meningioma (1); colorectal tumors (1); esophageal cancer (1); invasive carcinoma (1); malignant meningiomas (1); meningioma (1); mucinous adenocarcinoma (1).